INSC (INSC spindle orientation adaptor protein)
Description:
May function as an adapter linking the Par3 complex to the GPSM1/GPSM2 complex. Involved in spindle orientation during mitosis. May regulate cell proliferation and differentiation in the developing nervous system. May play a role in the asymmetric division of fibroblasts and participate in the process of stratification of the squamous epithelium (By similarity).
Tractability: Antibody: its Gene Ontology location is reachable by antibodies, with high confidence.
Gene: Protein-coding gene on chromosome 11 (15,112,424 to 15,247,208, forward strand). Ensembl gene ENSG00000188487.
Subcellular location: Cytoplasm; Cytoplasm, cell cortex
Gene Ontology:
Molecular function: protein binding; protein domain specific binding; protein-macromolecule adaptor activity; cytoskeletal anchor activity
Biological process: regulation of protein stability; apical protein localization; asymmetric cell division; establishment of mitotic spindle orientation; regulation of asymmetric cell division
Cellular component: cell cortex; cytoplasm; plasma membrane; protein-containing complex; raps-insc complex; apical cortex
Genetic constraint (gnomAD): Loss-of-function variants: 57 observed, 51.38 expected, observed/expected ratio (o/e) 1.11, 90% interval 0.9 to 1.38. The upper end of that interval is the gene's LOEUF score, 1.38, which puts it in group 5 of 6, group 1 being the genes least tolerant of losing a copy. Missense variants: 652 observed, 660.08 expected, observed/expected ratio (o/e) 0.99, 90% interval 0.93 to 1.05. Synonymous variants: 248 observed, 269.59 expected, observed/expected ratio (o/e) 0.92, 90% interval 0.83 to 1.02.
Homologues: Orthologues: chimpanzee INSC (99% identical), macaque INSC (98% identical), dog INSC (97% identical), rabbit INSC (95% identical), guinea pig INSC (95% identical), mouse Insc (94% identical), rat Insc (94% identical), pig INSC (94% identical), tropical clawed frog insc (64% identical), Drosophila melanogaster insc (23% identical), Caenorhabditis elegans insc-1 (21% identical).
Diseases named in the same sentence as INSC in open-access papers:
INSC is named in the same sentence as 16 diseases in open-access papers, as found by Europe PMC text mining. Sharing a sentence is not in itself a finding about the gene and the disease. The quoted sentences say what the papers report.
colon adenocarcinoma (2 papers, 2022). "The purpose of this study was to investigate the correlation of INSC gene with the level of immune infiltration and clinical prognosis in colon adenocarcinoma (COAD) patients." (PMID 36132082, 2022).
Charcot-Marie-Tooth disease (1 paper, 2024). An inherited degenerative disorder involving the peripheral nerves. "This study unveils the first discovery of an INSC gene missense mutation causing axonal Charcot-Marie-Tooth disease (CMT) and examines the microtubule-stabilizing role of PAR3/INSC/LGN in the adult peripheral nervous system (PNS)." (PMID 38589651, 2024).
diabetes (1 paper, 2024). "However, antigen identity is critical as artificial presentation of InsC-ChgA peptide on either MHC class I- or class II-expressing B cells prevents disease in a NOD.scid model of diabetes." (PMID 39211046, 2024).
glioblastoma (1 paper, 2017). The most malignant astrocytic tumor (WHO grade IV). "A somatic event also explain the fact that the InsC cannot be detected 1/ in the genetic material extracted from blood samples of controls and patients afflicted with a glioblastoma or with IPMT/CCP and 2/ in normal area of PanIN tissues." (PMID 27602750, 2017).
tumor (3 papers, 2022 to 2025). "The results showed that INSC was downregulated in higher pathological stage (P < 0.01), tumor stage (P < 0.001), and metastasis groups (P < 0.05)." (PMID 36132082, 2022). "This study aims to explore the diagnostic value of the INSC gene in COAD and its influence on tumor immune infiltration." (PMID 35664320, 2022). "The variables in the multivariate analysis included gender, age, tumor stage, lymph node status, metastasis, and INSC expression, and the results showed that age (P = 0.004), tumor stage (P = 0.028), metastasis (P < 0.001), and INSC expression (P = 0.033) were the ultimate influencers of OS." (PMID 36132082, 2022). "This suggests that INSC may play a specific role in tumor microenvironment and tumor immunity." (PMID 36132082, 2022). "Survival analysis found that the high expression of INSC was significantly correlated with poor overall survival in COAD, and the expression of INSC was related to COAD pathological stage, tumor stage, and metastasis." (PMID 36132082, 2022). "We show that SMOX inhibition does not affect the proliferation of GIC or iNSC; however, it promotes tumour cell migration, as assessed by wound healing assay, including assessment of gap closure and invasion." (PMID 39915814, 2025). "We discovered that INSC was depressed in a variety of tumor tissues compared to normal tissues as well as in COAD." (PMID 35664320, 2022). "In mammals, the function of the INSC gene is still unclear and never reported in tumor." (PMID 36132082, 2022).
cancer (2 papers, 2022). A tumor composed of atypical neoplastic, often pleomorphic cells that invade other tissues. "In the present study, we investigated the differential expression of INSC in pan-cancer, including COAD." (PMID 35664320, 2022). "Our study found that the expression of INSC was significantly downregulated in COAD, which regulated immune-infiltrating cells during cancer development and was associated with malignant progression in COAD patients." (PMID 36132082, 2022). "In human, the function of the INSC gene is still unclear, and the expression and mechanism of INSC in cancer are rarely reported." (PMID 36132082, 2022). "The differential expression of INSC mRNA in pan-cancer cells was next investigated." (PMID 35664320, 2022).
peripheral neuropathy (1 paper, 2024). A disorder affecting the peripheral nervous system. "Next, we investigated the impact of the human INSC mutation of p.M70R on peripheral neuropathy by establishing a fly model." (PMID 38589651, 2024).
INSC also shares sentences with these, for which no sentence is quoted: adrenocortical carcinoma (1 paper); bladder cancer (1); breast carcinoma (1); colon cancer (1); head and neck cancer (1); kidney cancer (1); lung carcinoma (1); prostate carcinoma (1); stomach adenocarcinoma (1).